GSTM3 (glutathione S-transferase mu 3)
Description:
Conjugation of reduced glutathione to a wide number of exogenous and endogenous hydrophobic electrophiles. May govern uptake and detoxification of both endogenous compounds and xenobiotics at the testis and brain blood barriers.
Synonyms: hGSTM3-3; GST5; GSTM3TV2; GSTB; GSTM3-3; GTM3
Tractability: Small molecule: it has a binding pocket of medium quality. PROTAC: UniProt records ubiquitination sites on it; ubiquitination databases record sites on it.
Target class: Enzyme; Transferase
Safety:
Unwanted effects reported when the protein is acted on. In parentheses: how it was acted on, where the effect was seen, and who reports it.
side effects (source: ClinPGx)
side effects (thrombocytopenia, anemia and neuropathy) (source: ClinPGx)
side effects (thrombocytopenia, anemia, and neuropathy) (source: ClinPGx)
Gene: Protein-coding gene on chromosome 1 (109,733,932 to 109,741,038, reverse strand). Ensembl gene ENSG00000134202.
Subcellular location: Cytoplasm
Subcellular location (Human Protein Atlas): Cytosol; Cytokinetic bridge; Microtubules; Primary cilium; Primary cilium tip; Primary cilium transition zone
Pathways (Reactome):
Metabolism: Glutathione conjugation
Gene Ontology:
Molecular function: enzyme binding; glutathione binding; glutathione transferase activity; identical protein binding; protein binding; protein homodimerization activity
Biological process: cellular detoxification of nitrogen compound; glutathione metabolic process; nitrobenzene metabolic process; response to estrogen; xenobiotic catabolic process; establishment of blood-nerve barrier
Cellular component: cytoplasm; cytosol; extracellular exosome; nucleus; sperm fibrous sheath
Genetic constraint (gnomAD): Loss-of-function variants: 20 observed, 23.77 expected, observed/expected ratio (o/e) 0.84, 90% interval 0.59 to 1.22. The upper end of that interval is the gene's LOEUF score, 1.22, which puts it in group 5 of 6, group 1 being the genes least tolerant of losing a copy. Missense variants: 241 observed, 255.23 expected, observed/expected ratio (o/e) 0.94, 90% interval 0.85 to 1.05. Synonymous variants: 95 observed, 89.96 expected, observed/expected ratio (o/e) 1.06, 90% interval 0.89 to 1.25.
Homologues: Orthologues: chimpanzee GSTM3 (99% identical), macaque GSTM3 (92% identical), pig GSTM3 (89% identical), rabbit GSTM3 (88% identical), rat Gstm5 (88% identical), mouse Gstm5 (88% identical), guinea pig GSTM3 (87% identical), dog GSTM3 (64% identical), zebrafish gstm.2 (64% identical), zebrafish gstm.1 (63% identical), zebrafish gstm.3 (62% identical), Caenorhabditis elegans gst-37 (24% identical), and 35 more. Paralogues in human: GSTM1 (71% identical), GSTM4 (70% identical), GSTM5 (70% identical), GSTM2 (67% identical), GSTP1 (29% identical), GSTA1 (24% identical), GSTA2 (24% identical), GSTA3 (24% identical), GSTA5 (24% identical), HPGDS (23% identical), GSTA4 (21% identical).
Diseases named in the same sentence as GSTM3 in open-access papers:
GSTM3 is named in the same sentence as 87 diseases in open-access papers, as found by Europe PMC text mining. Sharing a sentence is not in itself a finding about the gene and the disease. The quoted sentences say what the papers report.
breast carcinoma (9 papers, 2006 to 2025). "Studies have reported low GSTM3 expression in several types of tumors, and this has been found to be associated with cisplatin resistance in breast cancer." (PMID 25202346, 2014). "Studies have revealed that GSTM3 obviously affects the susceptibility of individuals to cancer, such as esophageal cancer, hepatocellular carcinoma, colorectal cancer, urinary bladder cancer, breast cancer, and prostate cancer." (PMID 34490047, 2021). "In pancreatic and breast cancers, GSTM3 upregulation has been shown to significantly reduce reactive oxygen species (ROS) accumulation and simultaneously inhibit tumor cell glycolysis, altering the metabolic phenotype of the tumor cells." (PMID 40740240, 2025). "Glutathione S-transferase Mu 3 (GSTM3) is another antioxidant overexpressed in MCF-7 breast cancer cells, while superoxide dismutase (SOD1) was overexpressed in PC3 prostate cancer cells." (PMID 38249992, 2024). "Regarding our findings, limited glucose resources and GLUL suppression decrease GSTM3 expression as a known metastatic gene in luminal breast cancer, and these findings further accentuate the significant role of GSTM3 in invasion potency, a major step in metastasis." (PMID 37780942, 2023). "Interestingly, genetic variants within the GSTM gene cluster—particularly in GSTM3—have been associated with cancer susceptibility in breast cancer, where certain GSTM3 SNPs conferred increased risk only in individuals lacking GSTM1 expression." (PMID 40868127, 2025). "Antioxidant proteins, including glutathione S-transferase Mu 3 and mitochondrial NADH dehydrogenase (ubiquinone) iron-sulfur protein 3, were overexpressed in breast cancer cells under zinc exposure." (PMID 38249992, 2024). "A proteomic analysis of MCF-7 breast cancer cells expressing constitutively active MEK5/Erk5, showed GSTM3 downregulation related to epithelial mesenchymal transition." (PMID 27206673, 2016). "SNP-SNP interactions in breast cancer development have been also reported in other studies, which targeted the SNPs of the carcinogen metabolism genes, including GSTM1, GSTT1, GSTP1, GSTM3 and CYPs." (PMID 16672066, 2006).
COVID-19 (8 papers, 2021 to 2025). A disease caused by infection with severe acute respiratory syndrome coronavirus 2. "The cumulative effect of risk genotypes across GSTP1 and GSTM3 was significant, with the risk of developing COVID-19 rising with each additional risk genotype." (PMID 40867811, 2025). "The combined GSTP1* and GSTM3* polymorphisms showed a cumulative risk regarding COVID-19 prevalence and severity." (PMID 37189435, 2023). "The results indicated a significant association between GSTP1 and GSTM3 polymorphisms and COVID-19 susceptibility and clinical manifestation." (PMID 37189435, 2023). "Combined GSTP1 (rs1695 and rs1138272) and GSTM3 genotype exhibited cumulative risk with regard to both COVID-19 occurrence and severity." (PMID 36834445, 2023). "GSTM1 and GSTT1 gene deletions as well as GSTP1 rs1138272 and rs1695, GSTA1 rs3957357, and GSTM3 rs1332018 polymorphisms have been investigated in a cohort of 207 COVID-19 patients and 252 healthy individuals of Serbian, Caucasian origin." (PMID 36009328, 2022). "Among six GST polymorphisms analyzed in this study, GSTP1 rs1695 and GSTM3 rs1332018 were found to be associated with COVID-19." (PMID 34988113, 2021). "Taken together, our results on the association between certain GSTP1 and GSTM3 genetic variants and COVID-19 have shed some light on the involvement of genetic susceptibility in COVID-19 development." (PMID 34988113, 2021). "Among six GST polymorphisms analyzed in this study, GSTP1 rs1695 and GSTM3 were found to be associated with COVID-19." (PMID 34988113, 2021). "Moreover, combined risk genotypes across GSTP1 and GSTM3 conferred higher risk for both incidence and severity of COVID-19 (p = 0.001 and p = 0.025, respectively)." (PMID 41209585, 2025). "Studies performed in a cohort of individuals of Serbian, Caucasian origin, revealed that individuals carrying the GSTP1-Val allele variant present lower odds of developing COVID-19; on the other hand, individuals carrying the GSTM3-CC allele variant present higher odds of developing COVID-19." (PMID 36834445, 2023). "Similarly, individuals with GSTM3*AC (rs1332018) variants showed lower odds of developing COVID-19 compared to the wild type GSTM3." (PMID 37189435, 2023). "Indeed, the data obtained showed that individuals carrying variant GSTP1-Val allele exhibit lower odds of COVID-19 development (p = 0.002), contrary to carriers of variant GSTM3-CC genotype which have higher odds for COVID-19 (p = 0.024)." (PMID 34988113, 2021). "Indeed, the data obtained showed that individuals carrying variant GSTP1-Val allele exhibit lower odds of COVID-19 development, contrary to the carriers of variant GSTM3-CC genotype who have higher odds for COVID-19." (PMID 34988113, 2021). "Moreover, combined GSTP1 (rs1138272 and rs1695) and GSTM3 genotype exhibited cumulative risk regarding both COVID-19 occurrence and COVID-19 severity (p = 0.001 and p = 0.025, respectively)." (PMID 34988113, 2021). "Moreover, combined GSTP1 (rs1138272 and rs1695) and GSTM3 genotype exhibited cumulative risk regarding both COVID-19 occurrence and COVID-19 severity." (PMID 34988113, 2021). "The carriers of GSTM3* (rs1332018) and GSTP1* (rs1695) heterozygotes and GSTP1* (rs1138272) Val allele showed a reduced risk of developing COVID-19 as compared to the wild-type carriers." (PMID 37189435, 2023). "The findings indicated that GSTM3 rs1332018 and GSTP1 rs1695 heterozygotes and carriers of the GSTP1 rs1138272 Val allele had decreased risk of developing COVID-19." (PMID 36009328, 2022). "Further pointing to the multifaceted role of GSTP1 as the dominant glutathione transferase class in lungs are the results regarding the role of combined GSTP1 (rs1138272 and rs1695) and GSTM3 genotype in both COVID-19 occurrence and severity." (PMID 34988113, 2021).
COVID-19 (continued). "Among six investigated GST polymorphisms, significant association between GST genotype and susceptibility for development of COVID-19 clinical manifestations was found for both GSTP1 (rs 1695 and rs1138272) and GSTM3 (rs1332018) polymorphisms." (PMID 34988113, 2021). "In a case–control study of 207 COVID-19 patients versus 252 matched controls, GSTP1 rs1695 (Ile105Val) variant carriers had significantly lower odds of developing COVID-19 (p = 0.002), while individuals with the GSTM3 CC genotype showed increased susceptibility (p = 0.024)." (PMID 41209585, 2025). "When GST genotypes distribution in COVID-19 patients and controls was assessed including adjustment for age, gender, smoking habit, and comorbidities, comprising hypertension, obesity, and diabetes, significant association remained for GSTP1 (rs1695) and GSTM3 (rs1332018) polymorphisms." (PMID 34988113, 2021). "In this line, it might be speculated that the presence of GSTM3-CC genotype in individuals with SARS-CoV-2 infection might significantly affect antioxidant capacity and consequential oxidative stress-associated mechanisms underlying COVID-19 development." (PMID 34988113, 2021). "Indeed, we found that the polymorphisms in GSTP1, GSTM3, GSTO1 and GSTO2 genes were associated with significant odds of COVID-19 development, while the combined GSTP1 and GSTM3 genotype even exhibited cumulative risk regarding both COVID-19 occurrence and COVID-19 severity." (PMID 35624818, 2022). "Several AD markers (CXCL10, TNFRSF1B, SPP1, TGFB1, GSTM3, and NKTR) have significantly altered expression in COVID-19 patients." (PMID 34108016, 2021). "The distribution of polymorphisms in cytosolic glutathione S-transferases GSTA1, GSTM1, GSTM3, GSTP1 (rs1695 and rs1138272), and GSTT1 were assessed in 207 COVID-19 patients and 252 matched healthy individuals, emphasizing their individual and cumulative effect in disease development and severity." (PMID 34988113, 2021). "We identified several AD marker genes (e.g., NKTR, GSTM3, TGFB1, TNFRSF1B, SPP1, and CXCL10) which may provide insights into the shared pathobiology of cognitive dysfunction in COVID-19 and AD." (PMID 34108016, 2021). "Instead, we found that GSTM3, known to be in linkage disequilibrium with GSTM1, meaning it might influence GSTM1 expression and possess overlapping substrate specificity with GSTM1, significantly contributes to COVID-19 development." (PMID 34988113, 2021).
bladder cancer (6 papers, 2016 to 2025). "One study demonstrated an interaction between GSTM3 deletion and smoking exposure: individuals with a GSTM3 deletion who smoke accumulate higher levels of carcinogens and DNA damage, which substantially increases their risk of bladder cancer." (PMID 40740240, 2025). "Subsequent colocalization analysis highlighted SLURP1, LY6D, WFDC1, NOV, and GSTM3 as being closely linked to bladder cancer occurrence." (PMID 40740240, 2025). "In summary, through a proteome-wide large-scale two-sample MR analysis combined with colocalization analysis, we identified SLURP1, LY6D, WFDC1, NOV, and GSTM3 as potential plasma proteins associated with bladder cancer." (PMID 40740240, 2025). "Similarly, among the 84 plasma proteins from the deCODE dataset, NOV and GSTM3 showed strong colocalization with bladder cancer risk (PP.H3+PP.H4 = 0.868 and 0.706, respectively)." (PMID 40740240, 2025). "Further validation showed that NOV and GSTM3 demonstrated robust causal associations with bladder cancer across multiple analytical methods, and molecular docking analysis revealed that these two proteins can bind to estrogen/progestin hormone-regulating drugs." (PMID 40740240, 2025). "A high GSTM3 expression was associated with worse survival among bladder cancer patients." (PMID 32984010, 2020). "Regarding GSTM3, mutation of this gene may increase the risk of bladder cancer." (PMID 32539715, 2020). "A total of 199 plasma proteins were found to be significantly associated with bladder cancer risk, among which five proteins (SLURP1, LY6D, WFDC1, NOV, and GSTM3) emerged as core candidate targets." (PMID 40740240, 2025). "These discoveries, along with our proteomics-based findings (NOV, GSTM3), highlight the expanding landscape of potential targets for bladder cancer therapy." (PMID 40740240, 2025). "In bladder cancer, patients with low GSTM3 expression exhibited the highest survival probability, whereas whose with normal or high GSTM3 expression had lower survival probability." (PMID 33482859, 2021). "A similar mechanism likely applies to bladder cancer, where GSTM3's detoxification and antioxidant functions might suppress tumor growth by mitigating oxidative stress and metabolic reprogramming." (PMID 40740240, 2025). "Therefore, NOV and GSTM3 can be prioritized as bladder cancer biomarkers or therapeutic targets for in-depth research." (PMID 40740240, 2025). "The fact that NOV and GSTM3 showed consistent associations across MR, colocalization, and SMR (with negative HEIDI) suggests that their gene expression levels may influence bladder cancer risk through a direct and singular pathway." (PMID 40740240, 2025). "As we conducted an in-depth analysis of bladder cancer mechanisms, NOV and GSTM3 emerged as potential druggable targets." (PMID 40740240, 2025). "In a global DNA methylation analysis of treatment-naïve bladder cancer patients, the DNA methylation in the GSTM2 and GSTM3 promoter was found to be higher in invasive tumors than in non-invasive types." (PMID 27404495, 2016).
glioma (6 papers, 2010 to 2024). A benign or malignant brain and spinal cord tumor that arises from glial cells (astrocytes, oligodendrocytes, ependymal cells). "Various studies have shown that lncRNA GAS5 also plays a role in the brain, in fact lncRNA GAS5 can effectively inhibit the proliferation, migration and invasion of glioma cells and promote cell apoptosis through targeting GSTM3 expression." (PMID 32624686, 2020). "Another large-scale study obtained data indicating the absence of an association between polymorphisms of GSTM1 (Ins/Del), GSTM3 (A63С), GSTT1 (Ins/Del) and the development of gliomas, glioblastomas, and meningiomas." (PMID 22649665, 2010). "GAS5 lncRNA targets GSTM3, so it is expressed in glioma cells compared to glial cells." (PMID 37620425, 2023). "Furthermore, due to the regulatory nature of lncRNAs, GAS5 was shown to be able to bind to GSTM3 in glioma cells." (PMID 37047296, 2023).
hepatocellular carcinoma (6 papers, 2014 to 2024). A malignant tumor that arises from hepatocytes. "On the one hand, GSTM3 influences the malignant metabolic pattern in pancreatic cancer, alleviates aggressiveness in renal cell carcinoma, and reverses radioresistance in hepatocellular carcinoma to suppress tumour malignancy." (PMID 38228715, 2024). "Meanwhile, an increase in Gstm3 expression might alleviate liver fibrosis, and Gstm3 could serve as a potential radiotherapy target for patients with hepatocellular carcinoma." (PMID 39330516, 2024). "Moreover, GSTM3 reverses the radioresistance through cell cycle arrest and apoptosis facilitation in hepatocellular carcinoma." (PMID 38228715, 2024). "The purpose of the present study was to investigate the role of GSTM3 in reversing radioresistance, and to explore the molecular mechanism of this in the human radiation-resistant PRF/PLC/5R hepatocellular carcinoma (HCC) cell line." (PMID 25202346, 2014).
cervical cancer (5 papers, 2018 to 2025). A primary or metastatic malignant neoplasm involving the cervix. "For example, in cervical cancer, GSTM3 has been reported to regulate the NF-κB and MAPK signaling pathways, playing a crucial role in tumor cell survival, proliferation, and anti-apoptotic functions." (PMID 40740240, 2025). "Hence, we suggest GSTM3 and GSTP1 as novel biomarkers and potential therapeutic targets for treating cervical cancer." (PMID 29774096, 2018). "Moreover, GSTM3 and GSTP1 are involved in cell survival and proliferation in cervical cancer cell lines, but information is not available regarding their function in GBM." (PMID 34209254, 2021).
colon cancer (5 papers, 2016 to 2021). "Meding S reported that high GSTM3 expression correlated with lymph node metastasis and advanced stage of colon cancer, and low GSTM3 expression was associated with better survival." (PMID 33482859, 2021). "Downregulation of GSTM3 (glutathione-S-transferase Mu 3) was associated with metastasis in clear-cell renal-cell carcinoma and breast and colon cancer cells." (PMID 27206673, 2016). "GSTM1, GSTM2, and GSTM3 were expressed at significantly higher levels in normal tissues than in colon tumor tissues." (PMID 32539715, 2020). "The protein expression of GSTM3 has been analyzed in colon cancer, and its overexpression is considered a marker of regional lymph node metastasis." (PMID 29774096, 2018).
lung carcinoma (5 papers, 2017 to 2021). "Indeed, in the case of GSTM3, a null genotype yielding low expression, is reportedly associated with reduced lung cancer risk." (PMID 33777753, 2021). "Moreover, low expression of GSTM3, which is involved in “drug metabolism-cytochrome P450”, correlates with increased susceptibility to lung cancer." (PMID 32518519, 2020). "It has been demonstrated that GSTM3 is associated with cancer risk at a genetic level, where the association of certain polymorphisms and/or mutations increases the risk of different types of cancer, such as lung cancer, prostate cancer, and colorectal cancer." (PMID 29774096, 2018). "Particularly, GSTP1 and GSTM3 have been reported as being dysregulated in cancers such as: prostate cancer, triple-negative breast cancer, lung cancer, and colorectal cancer." (PMID 29774096, 2018). "Although early research suggested a weak association exists between certain GST gene mutations (e.g., GSTM1, GSTM3, GSTP1, and GSTT1) and risk of lung cancer, more recent work has not evidenced any definitive links between GSTM3 polymorphisms and lung cancer risk." (PMID 33568630, 2021). "In particular, frequent alteration in GSTT1, ALDH3A3, CBR1 and GSTM3 showed non-redundant events in the three lung cancer subtypes (Z score=2.00, empirical P<0.05)." (PMID 28581523, 2017).
renal cell carcinoma (5 papers, 2020 to 2025). "However, GSTM3 acts as a tumour suppressor to inhibit tumourigenesis in gastric cancer, alleviate the aggressiveness in renal cell carcinoma, and alter the malignant metabolic pattern in pancreatic cancer." (PMID 38228715, 2024). "In a study on renal cell carcinoma (RCC), GSTM3 was not only downregulated in primary RCC tissues compared with adjacent normal renal tissues but also downregulated in metastatic RCC cells compared with primary RCC cells." (PMID 33482859, 2021). "It has been reported that GSTM3 may function as a tumor suppressor in renal cell carcinoma." (PMID 32392242, 2020).